IGHD6-13 (immunoglobulin heavy diversity 6-13)
Synonyms: IGHD613; DN1
Gene: Immunoglobulin diversity (D) gene on chromosome 14 (105,901,142 to 105,901,162, reverse strand). Ensembl gene ENSG00000211920.
Diseases named in the same sentence as IGHD6-13 in open-access papers:
IGHD6-13 is named in the same sentence as 2 diseases in open-access papers, as found by Europe PMC text mining. Sharing a sentence is not in itself a finding about the gene and the disease.
IGHD6-13 shares sentences with these, for which no sentence is quoted: infection (1 paper); systemic juvenile idiopathic arthritis (1).